STAT3 (signal transducer and activator of transcription 3)
Diseases named in the same sentence as STAT3 in open-access papers (continued):
Sharing a sentence is not in itself a finding about the gene and the disease.
liver failure (3 papers, 2018 to 2023). A liver disease characterized by the liver losing or has lost all of its function. "Similarly, in hepatic failure mice, suppression of the IL-6/STAT3 signaling pathway has been associated with a substantial alleviation in both liver injury and inflammatory responses, as well as a decrease in AST and ALT levels." (PMID 38139043, 2023). "Among the most sensitive parameters affecting time to liver failure are steady-state production of Tgfb by HSCs (KSSTgfb), concentration of monomeric STAT3 ([STAT3]), IE gene activation rate (VIE), and quiescent-to-primed transition rate (kQ → P)." (PMID 30285726, 2018). "Although not in the top 20 highest sensitivity parameters, monomeric STAT-3 concentration shows a positive contribution to both regeneration and liver failure." (PMID 30285726, 2018).
male infertility (3 papers, 2022 to 2025). The inability of the male to effect fertilization of an ovum after a specified period of unprotected intercourse. "The results further emphasized the regulatory role of JAK2/STAT3 on spermatogenesis, Keap1/Nrf2 signaling, and maintenance of the testicular redox balance to combat testicular dysfunction and male infertility." (PMID 37759514, 2023). "The results emphasized the regulatory role of JAK2/STAT3, NLRP3/Caspase-1 signaling in testicular tissue maintenance to resist PbAc-induced dysfunctions and male infertility." (PMID 40356721, 2025).
malignant mesothelioma (3 papers, 2017 to 2022). A malignant neoplasm of the pleura or peritoneum, arising from mesothelial cells. "We previously reported that in malignant mesothelioma (MM), low PIAS3 expression is associated with increased STAT3 activation and correlates with poor patient survival, yet the regulatory mechanism(s) governing PIAS3 expression in MM remain unclear." (PMID 30259640, 2018).
mesenchymal tumors (3 papers, 2020 to 2022). "Hallmarks of the Mesenchymal subtype, including a slight global DNA hypermethylation, enrichment of the hazardous RETM918T mutation, and STAT3 signaling activation, may be causally related and collectively serve as molecular determinants of poorer prognosis in Mesenchymal tumors." (PMID 36344509, 2022).
mood disorder (3 papers, 2022 to 2025). A cognitive disorder a disturbance in which the person's mood is hypothesized to be the main underlying feature. "Evidence suggests that IL-6 can regulate serotonin transporter (SERT) expression and function, mediated by STAT3 activation, and systemic blockage of STAT3 leads to altered behavioral phenotypes relevant to mood disorders." (PMID 37938494, 2023). "The excessive expression of inflammatory factors can activate the JAK1/STAT3 pathway, which may lead to hippocampal neuronal damage, impair learning and memory abilities, and exacerbate mood disorders." (PMID 40076470, 2025). "The role of STAT3 in mood disorders has been indicated by several lines of evidence in terms of STAT3 activity, serotonergic neurotransmission, and the control of behaviors relevant to psychopathology; however, evidence for STAT3 in the course of OCD is still limited." (PMID 35887540, 2022).
MRSA pneumonia (3 papers, 2020 to 2025). "STAT3-mediated induction of the antimicrobial protein REG3G is required for host defense against methicillin-resistant Staphylococcus aureus pneumonia." (PMID 33488611, 2020).
myasthenia gravis (3 papers, 2020 to 2025). Myasthenia gravis (MG) is a rare, clinically heterogeneous, autoimmune disorder of the neuromuscular junction characterized by fatigable weakness of voluntary muscles. "This receptor-specific mechanism was validated through anti-IL-18Rα blocking experiments, revealing a divergent signaling axis compared with the SIGIRR/STAT3 pathway reported in Myasthenia Gravis." (PMID 40427088, 2025).
mycosis fungoides (3 papers, 2014 to 2015). Classical mycosis fungoides is the most common type of mycosis fungoides (MF), a form of cutaneous T-cell lymphoma, and is characterized by slow progression from patches to more infiltrated plaques and eventually to tumors. "AG490, the most popular STAT3 inhibitor, can induce CC cell apoptosis and inhibit CC/mycosis fungoides tumor cell proliferation." (PMID 25344679, 2014). "In mycosis fungoides tumor cells, some apoptosis-related genes, such as Bcl-2 and Bax, have been identified as STAT3 target genes." (PMID 25092271, 2014).
neck cancers (3 papers, 2009 to 2020). "Constitutive Stat3 activity has been observed in many cancers, including prostate, squamous cell, breast, head, and neck cancers, and has been associated with a poor prognosis." (PMID 20030845, 2009).
nephrolithiasis (3 papers, 2024 to 2025). The presence of a calculus in the pelvis of the kidney; this is most often composed of mineral salts and proteins. "Given the well-established role of IGF1R in influencing STAT3 phosphorylation, this study focused on the regulation of downstream LDHA by JAK2/STAT3 signaling axis and its role in kidney stone formation." (PMID 39744436, 2025). "To summarize, targeted inhibition of PKA and STAT3 can attenuate the stimulatory impact of CaSR on claudin-14, thus inhibiting kidney stone formation." (PMID 39697555, 2024). "To further elucidate the role of PKA and STAT3 in the CaSR-claudin-14 pathway, we treated a rat model of ethylene glycol-induced kidney stones by co-administering the CaSR activator R568 along with the PKA inhibitor or the STAT3 inhibitor." (PMID 39697555, 2024). "Importantly, we are the first to reveal the role of the IGF1R-JAK2/STAT3-LDHA axis in regulating glycolysis and EMT in a kidney stone model, offering a fresh perspective on the metabolic mechanisms underlying kidney stone injury." (PMID 39744436, 2025).
ocular hypertension (3 papers, 2013 to 2021). Abnormally high intraocular pressure. "To shed more light on this idea, we measured the changes in the mRNA expression of transcription factors STAT1, STAT2, and STAT3 and found that mRNA levels of all STATs were increased in the retina of ocular hypertensive animals." (PMID 33628191, 2021). "The mRNA expression of STAT1, STAT2, and STAT3 was increased significantly in the retina of ocular hypertensive animals." (PMID 33628191, 2021). "Conversely, we have seen a significant increase in the acetylation of STAT3 at lysine 685 (Ac-K685) by SNC-121 treatment in ocular hypertensive animals." (PMID 33628191, 2021). "Stattic, a selective STAT3 inhibitor, administration resulted in a complete attenuation in the production of IL-1β and IL-6 in ocular hypertensive animals." (PMID 33628191, 2021). "Our data provides evidence that phosphorylation of STAT3 at tyrosine 705 is significantly (p < 0.0001) increased in the retina of ocular hypertensive animals." (PMID 33628191, 2021). "Mechanistically, we provide data showing a significant increase in the phosphorylation of STAT3 at tyrosine 705 whereas a moderate but significant increase in the total STAT3 protein expression was also seen in the retina of ocular hypertensive animals." (PMID 33628191, 2021). "In this study, we investigated the role of STAT3 in regulating the activation of astrocytes to transient intraocular hypertension in vivo by using a rat ocular hypertension model." (PMID 23383263, 2013). "Additionally, transcription factor (STAT3) activation and phosphorylation at tyrosine 705 is significantly increased in ocular hypertensive animals." (PMID 33628191, 2021). "Furthermore, we have seen 144 ± 17% (p = 0.02) increase in the total STAT3 protein expression in ocular hypertensive retina when compared with naïve retina." (PMID 33628191, 2021). "Moreover, we have seen a significant increase in the STAT3 acetylation at lysine 685 (AcK685) by SNC-121 treatment in ocular hypertensive animals." (PMID 33628191, 2021). "Interestingly, acetylation of STAT3 at lysine 685 (AcK685) was reduced in ocular hypertensive animals and subsequently increased significantly by SNC-121 treatment." (PMID 33628191, 2021). "Interestingly, up-regulation of STAT1, STAT2, and STAT3 mRNA was blocked in SNC-121 treated ocular hypertensive animals." (PMID 33628191, 2021). "We have shown that both LIF and STAT3 mRNA expression and STAT3 phosphorylation at tyrosine 705 were increased in the ocular hypertensive animals, which were fully blocked by SNC-121 treatment, suggesting that LIF might be required for the STAT3 activation for pro-inflammatory cytokines production." (PMID 33628191, 2021). "Phospho-STAT3 immunostaining was remarkably increased in retinal ganglion cell (GCL) and nerve fiber layers, however, a diffuse and punctate immunostaining was also seen in inner nuclear and outer plexiform layers of ocular hypertensive animals." (PMID 33628191, 2021).
Pancytopenia (3 papers, 2021 to 2024). An abnormal reduction in numbers of all blood cell types (red blood cells, white blood cells, and platelets). "For patient 6, no targeted treatment has been employed so far, as sirolimus was started a year prior to the diagnosis of STAT3-GOF and led to satisfactory control of autoimmune pancytopenia and lymphadenopathy." (PMID 39247195, 2024).
Peri-Implantitis (3 papers, 2023). An inflammatory process with loss of supporting bone in the tissues surrounding functioning DENTAL IMPLANTS. "Recent studies have shown that patients with peri-implantitis have increased expression ofpro-inflammatory cytokines, such as IL-6 and STAT-3." (PMID 37822839, 2023). "Thus, pro-inflammatory cytokines such as IL-6 and STAT-3 are oftenexpressed in the tissue of patients with peri-implantitis, highlighting the importance of preventing chronic inflammation in implant patients." (PMID 37822839, 2023). "The complex formed with sIL-6R in peri-implantitis lesions and IL-6 produced from Clys-stimulated HGFs exacerbates the inflammatory response to produce IL-8, IL-6, and pro-MMP-1 and activate the gp130/STAT3 pathway." (PMID 36834667, 2023).
Pleural effusion (3 papers, 2015 to 2021). The presence of an excessive amount of fluid in the pleural cavity. "Such as formation of foamy macrophages by TB pleural effusions is triggered by the interleukin‐10/signal transducer and activator of transcription 3 Axis through ACAT upregulation." (PMID 34773365, 2021).
polyarteritis nodosa (3 papers, 2020 to 2021). Polyarteritis nodosa (PAN) is a rare, clinically heterogeneous, rheumatologic disease characterized by necrotizing inflammatory lesions affecting small- and medium-sized blood vessels. "The high level of stat activation is associated with Pan-cancers, especially for Stat3 and Stat5, which is mostly related to more dangerous tumors." (PMID 31907037, 2020). "However, some hints of a potential role of JAK/STAT may come from the evidence of an upregulation of STAT3 in the PB CD4+ and CD8+ T cells of polyarteritis nodosa (PAN) patients and of increased levels of CXCL10 (a STAT induced gene) in active Kawasaki disease." (PMID 33854436, 2021).
rectum adenocarcinoma (3 papers, 2020 to 2025). An adenocarcinoma arising from the rectum. "We found significant correlations between expression levels of STAT2 and those of STAT3 and cyclin D1, respectively, in tumor samples from colon and rectum adenocarcinoma." (PMID 38001683, 2023). "In rectal adenocarcinoma, an ETV4/Hes1/STAT3 signaling axis has been identified: the transcription factor ETV4 activates Hes1 transcription by binding to its promoter, which subsequently drives STAT3 phosphorylation to promote tumor proliferation and metastasis." (PMID 40755759, 2025).
reflux esophagitis (3 papers, 2017 to 2023). "In conclusion, our results demonstrated that exosomal miR-29a-3p might assist in the diagnosis of GERD, and increased expression of esophageal miR-223-3p was inversely associated with expression of E2F1 or STAT3 in esophageal tissue reflux esophagitis." (PMID 28757556, 2017).
relapsing-remitting MS (3 papers, 2010 to 2021). "Phosphorylated STAT3 (pSTAT3) was significantly higher in CD4+ T cells from relapsing-remitting MS (RRMS) patients in relapse compared with those in remission and healthy controls (HCs)." (PMID 33411696, 2021). "With this study, we investigated the IL-12/STAT4, IL-23/STAT3, and IL-6/STAT3 pathways in patients with relapsing-remitting MS (RRMS) and the potential impact of genetic background on activation of these pathways." (PMID 30917537, 2019).
retinal diseases (3 papers, 2020 to 2024). "While Ref-1 controls a number of TFs that are under redox regulation, three have been found to directly link cancer studies to retinal diseases; HIF-1α, NF-κB and STAT3." (PMID 34322687, 2021).
retinal ischemia (3 papers, 2025). A ischemic disease that involves the retina. "Curcumin was also demonstrated to protect retinal neurons and microvessels in retinal ischemia–reperfusion injury by inhibiting the NF-κB and signal transducer and activator of transcription 3 (STAT3) pathways." (PMID 41515186, 2025).
retinitis pigmentosa (3 papers, 2016 to 2024). Retinitis pigmentosa (RP) is an inherited retinal dystrophy leading to progressive loss of the photoreceptors and retinal pigment epithelium and resulting in blindness usually after several decades. "Photoreceptor-specific deletion of STAT3 accelerates photoreceptor degeneration, whereas the expression of dominant active STAT3 improves photoreceptor survival in two models of retinitis pigmentosa." (PMID 27242532, 2016). "The expression of Müller cell gliosis genes known to be dysregulated in retinal pathologies such as retinitis pigmentosa, but also in DR, such as Stat3, S100a1 or CD44, were plotted to further validate the gliotic activation in our db/db mice at the molecular level." (PMID 38273366, 2024).
rheumatic heart disease (3 papers, 2021 to 2023). An autoinflammatory condition following an infection with Group A Beta Hemolytic Streptococcus (GABHS), in which the heart is attacked by antibodies formed in reaction to a recent GABHS infection. "Additionally, in rheumatic heart disease, overexpression of S1PR1 reduces p-STAT3 levels and Th17-associated cytokines RORγt, IL-6 and IL-17." (PMID 37858140, 2023). "In rheumatic heart disease, miR‐155 aggravated the valve injury through S1PR1, SOCS1/STAT3 and IL‐6/STAT3 signalling pathways." (PMID 33664937, 2021).
schistosomiasis (3 papers, 2020 to 2023). An infectious disease caused by parasitic trematodes of the genus Schistosoma that colonize human blood vessels and release eggs that can cause granulomatous reactions leading to acute (swimmer's itch or acute schistosomiasis syndrome) or chronic disease. "The activation of the STAT3 signaling pathway and its mediation of inflammation, oxidative stress, cell proliferation, and apoptosis promote schistosomiasis egg-induced liver injury, which causes subsequent hepatic dysfunction, granuloma formation, and the initiation of fibrosis." (PMID 36986363, 2023). "Hepatic injury caused by schistosomiasis was exacerbated by the accumulation of reactive oxygen species, which activated JAK2 and STAT3." (PMID 37339146, 2023). "A combination of clinical evidence and animal studies suggests that schistosomiasis can trigger hepatocellular carcinogenesis through the activation of c-Jun and STAT3 in response to soluble egg antigens." (PMID 37339146, 2023).
sclerosing cholangitis (3 papers, 2015 to 2025). A chronic, autoimmune inflammatory liver disorder characterized by narrowing and scarring of the lumen of the bile ducts. "Especially, conditionally-inactivated STAT3 in hepatocytes and cholangiocytes led to strongly aggravated hepatocellular damage and fibrosis in a sclerosing cholangitis animal model using mice lacking the multidrug resistance gene 2 (mdr2−/−)." (PMID 26308055, 2015).
Shock (3 papers, 2010 to 2025). The state in which profound and widespread reduction of effective tissue perfusion leads first to reversible, and then if prolonged, to irreversible cellular injury. "In summary, this study revealed the critical involvement of the IL-6/JAK/STAT3, PI3K/Akt/mTOR, and TNF-α/NF-κB pathways in pediatric postoperative septic shock and identified key genes such as PIM3, with quercetin and astramembrannin I predicted as potential therapeutic compounds." (PMID 41189212, 2025).
silicosis (3 papers, 2020 to 2024). Silicosis is a respiratory disease caused by breathing in (inhaling) silica dust. "Our findings clearly support the theory that BIC reduces inflammation in silicosis via inhibitory effects on the JAK2/STAT3/SOCS3 signaling pathway." (PMID 39060930, 2024). "Consistently, abnormally activated JAK2 and STAT3 as well as aberrantly expressed SOCS3 in lung tissues of silicosis rats were downregulated by BIC in the silicosis model." (PMID 39060930, 2024). "Our study also showed that PTPN2 can inhibit epithelial-mesenchymal transition by dephosphorylating STAT3 in silicosis fibrosis." (PMID 32054021, 2020). "PTPN2 can inhibit EMT by dephosphorylating STAT3 in silicosis fibrosis." (PMID 32054021, 2020). "JAK2 and STAT3, crucial proteins in the JAK/STAT signaling pathway, play a significant role in regulating macrophage polarization in silicosis; inhibiting the expression of these proteins can delay the progression of silicosis." (PMID 37381044, 2023). "Hence, inactivation of JAK2/STAT3 signaling in macrophages may not be the only mechanism by which BIC reduces inflammation during silicosis." (PMID 39060930, 2024). "Similarly, in our silicosis model, both JAK2 and STAT3 were activated by TGF-β1 in fibroblasts, but not the other three cytokines, leading to promotion of the FMT process and wound healing." (PMID 39060930, 2024).
skin papilloma (3 papers, 2013 to 2017). A benign papillary neoplastic growth on the skin composed of epithelial cells and a fibrous stalk. "In our study, the repeated UVB irradiation caused Tyr705 phosphorylation of STAT3 in the skin papillomas, and this was attenuated in fat-1 transgenic mice and DHA-treated WT mice." (PMID 28912452, 2017). "Stat3 is constitutively activated in both skin papilloma and carcinomas and is linked to cSCC." (PMID 27102301, 2016). "In this regard, loss of Stat3 completely suppressed the development of skin papillomas." (PMID 23577258, 2013). "Moreover, intratumoral injection of Stat3 decoy caused regression in preexisting skin papillomas." (PMID 23577258, 2013). "DHA treatment also significantly dampened the phosphorylation of STAT3 at the Tyr705 in the skin papillomas (lower)." (PMID 28912452, 2017). "In this regard, deletion of Stat3 in skin papillomas by i.p. injection of tamoxifen inhibited subsequent growth of these tumors." (PMID 23577258, 2013). "The availability of an inducible Stat3 knockout model also allowed deletion of Stat3 in skin papillomas generated by the DMBA-TPA protocol." (PMID 23577258, 2013). "In addition, Stat3 is upregulated and constitutively activated in skin papillomas and SCCs generated by the two-stage protocol." (PMID 23577258, 2013). "Finally, the use of these models demonstrated the requirement for Stat3 activation for continued growth of skin papillomas." (PMID 23577258, 2013).
status epilepticus (3 papers, 2020 to 2025). Status epilepticus is defined as a continuous seizure lasting more than 30 min, or two or more seizures without full recovery of consciousness between any of them. "Results obtained in experimental animal models and human patients have indicated that after status epilepticus, the chemokine CCL2-CCR2 signal induces neuronal cell death through the activation of STAT3 and the production of IL-1β." (PMID 34511129, 2021).
testicular germ cell tumor (3 papers, 2021 to 2025). A germ cell tumor arising from the testis. "Increased STAT3 expression is also relevant in testicular germ cell tumors (TGCT)." (PMID 36977736, 2023).